STAT3 (signal transducer and activator of transcription 3)
Diseases named in the same sentence as STAT3 in open-access papers (continued):
Sharing a sentence is not in itself a finding about the gene and the disease.
ovarian carcinoma (continued). "Adding STAT3-inhibitors on ovarian cancer cells and treating them with cisplatin increases their sensitivity, leading to the hypothesis that hypoxic ovarian cancer cell-derived exosomes play an important role in the development of resistance toward this drug." (PMID 36831417, 2023). "IL-6 was found to activate the JAK/STAT3 pathway and could promote tumor metastasis in ovarian cancer by enhancing the proliferation, migration, and invasion of tumor cells." (PMID 38038814, 2023). "Both SRC and STAT3 are regarded as potential targets in ovarian cancer treatment." (PMID 37831733, 2023). "Thus, it is crucial to search for STAT3 inhibitors in order to develop effective therapeutic interventions for ovarian cancer." (PMID 37238935, 2023). "Interestingly, bazedoxifene, which is also a selective estrogen receptor modulator inhibiting gp130/STAT3 signaling, was recently studied in ovarian cancer." (PMID 36672405, 2023). "The global role of STAT3 in the acquisition of a CSC phenotype in ES2 tumorsphere or in a commercially available ovarian cancer-derived CSC (OvCSC) model was further explored in terms of functional chemotactic response to the bioactive JAK/STAT3 inducer lysophosphatidic acid (LPA)." (PMID 37189618, 2023). "Based on current bioinformatics data, we might extrapolate that SRC and STAT3 were core pharmacological targets in pachyman treating ovarian cancer through regulating ferroptosis." (PMID 37831733, 2023). "To determine whether STAT3 and NOTCH1 signaling pathways are implicated in CD109-induced drug resistance in ovarian cancer cells, we examined the effects of STAT3 and NOTCH1 inhibitors on CD109-induced drug resistance." (PMID 37373457, 2023). "Furthermore, cisplatin-sensitive OV2008 and A2780 ovarian cancer cell lines treated with IL-6, which activates STAT3, showed increased cisplatin resistance." (PMID 38067351, 2023). "Thus, CAFs play a crucial role in promoting ovarian cancer cell growth by regulating STAT3/PI3K/Akt pathway." (PMID 37065872, 2023). "Additionally, exosomes derived from cell lines of ovarian cancer patients’ ascites are characterized by an increased concentration of STAT3 and FAS in their cargo." (PMID 38132461, 2023). "In this study, the effects of LicA on proliferation, apoptosis, and cell cycle arrest of SKOV3 human epithelial ovarian cancer cells were determined and a possible mechanism involved in anti-cancer activity of LicA against ovarian cancer through STAT3-mediation was identified." (PMID 37238935, 2023). "At the clinical level, there is increasing evidence that activation of the STAT3 pathway significantly correlates with reduced survival of rare ovarian cancers, thereby highlighting the importance of STAT3 as a prospective therapeutic target for cancer treatment." (PMID 36288633, 2022). "STAT3 activity is induced by hypoxia and not only regulates proliferation under hypoxic conditions, but also confers both cisplatin and paclitaxel resistance, in part by priming ovarian cancer stem cells to survive in adverse conditions." (PMID 35326569, 2022). "TRIM47 knockdown in ovarian cancer cells resulted in a substantial reduction in p-STAT3 levels." (PMID 36288633, 2022). "Furthermore, CAFs can activate the anti-apoptotic signal STAT3, thereby reducing cisplatin-induced apoptosis and promoting chemoresistance in ovarian cancer." (PMID 35739532, 2022). "M2 TAMs in coculture with SKOV3 ovarian cancer cells increased STAT3 activation." (PMID 35565348, 2022). "In addition, ovarian cancer cells expressing STAT3 showed increased resistance to chemotherapy and with cancer stem cells (CSCs) or CSC-like phenotypes." (PMID 36524006, 2022). "Additionally, studies have demonstrated downregulation of the STAT3 pathway with siRNA suppresses ovarian cancer proliferation and induces apoptosis in vitro." (PMID 35565348, 2022).
ovarian carcinoma (continued). "Previously, research has illustrated that CAFs secrete CCL5 in response to cisplatin treatment in ovarian cancer to increase resistance, which may be achieved through modulation of STAT3 and PI3K/Akt pathways." (PMID 35739532, 2022). "Indeed, it has been shown that inflammatory cytokines, such as IL17A, increase lipid uptake in ovarian cancer cells via the STAT3/FABP4 axis, leading to enhanced growth both in vitro and in vivo." (PMID 35565396, 2022). "IL-17 also activates the STAT3 pathway, inducing proliferation of ovarian cancer cells." (PMID 35574025, 2022). "•TRIM47 promoted ovarian cancer cell proliferation and invasion via STAT3 signaling." (PMID 36288633, 2022). "EGFR could activate a variety of downstream pathways, such as the ERK, AKT and STAT3 pathways, in ovarian cancer cells." (PMID 34369236, 2021). "Thus, the anti-IL-6 antibody siltuximab has been shown to reduce STAT3 activation and angiogenesis in IL-6-producing xenografts of intraperitoneal ovarian cancer and reduces VEGF levels in patients with ovarian cancer." (PMID 34206393, 2021). "Prevalent evidence uncovered the roles of STAT3 in ovarian cancer." (PMID 34539736, 2021). "However, NO also induces anti-apoptosis of ovarian cancer cells through modulating STAT3 phosphorylation." (PMID 34356634, 2021). "Next, we determined whether the introduction of STAT3 cDNA could reverse the effect of FBP1 in ovarian cancer cells." (PMID 34363022, 2021). "In addition, studies have also shown that STAT3 in conjunction with paclitaxel therapy synergistically reduced peritoneal seed and extended survival in the murine model of intraperitoneal ovarian cancer." (PMID 33809542, 2021). "As SOCS3 has a low expression level in ovarian cancer tissues and positively correlated with the level of NR1D1, we speculate that NR1D1 may influence the JAK/STAT3 signaling pathway as well as ovarian cancer cell growth through modulating SOCS3." (PMID 34330232, 2021). "Lastly, we investigated whether increased STAT3 signaling observed in Olaparib-resistant ovarian cancer cell lines can promote paracrine STAT3 activation in tumor microenvironment." (PMID 34956861, 2021). "Elevated STAT3 expression was identified in ovarian cancer ascites and could promote invasion and metastasis." (PMID 34539736, 2021). "Similarly, STAT3 signaling in CAFs has been previously shown to promote stemness, drug resistance, and immunosuppression in several cancer types, including ovarian cancer." (PMID 34956861, 2021). "Six studies (7 trials) investigated the association between STAT3/p-STAT3 expression and the subtype (mucinous vs. nonmucinous; endometrioid vs. nonendometrioid) of ovarian carcinoma in 1204 patients." (PMID 34789292, 2021). "In addition, IL-6 can induce nuclear translocation and elevate the transcriptional activity of HIF-1α via STAT3 signalling to enhance the chemoresistance against cisplatin of ovarian cancer cells." (PMID 35004308, 2021). "Notably, we show that STAT3 activation is elevated in Olaparib-resistant ovarian cancer cells, and genetic or pharmacological STAT3 inhibition can effectively reduce PARPi-resistant cell proliferation." (PMID 34956861, 2021). "Finally, we demonstrate that the acquisition of PARPi resistance in ovarian cancer cells was accompanied by increased STAT3 activity." (PMID 34956861, 2021). "Notably, in replicatively senescent ovarian cancer cells, the STAT3 level was among the pathways whose level declined." (PMID 34674640, 2021). "In this study, we found that increased STAT3 activity after EGFR knockdown could partially explain the unsatisfactory results of anti-EGFR targeted therapy in ovarian cancer patients." (PMID 34369236, 2021). "We wonder how NR1D1 influences the JAK/STAT3 signal in ovarian cancer cells." (PMID 34330232, 2021). "However, EGFR inhibitor treatment similarly resulted in increased STAT3 phosphorylation in human ovarian cancer cells." (PMID 34369236, 2021).
ovarian carcinoma (continued). "Based on the results, this research suggested that NO donor could induce ovarian cancer cell apoptosis through inhibiting STAT3 and Akt phosphorylation, which was confirmed by incubating ovarian cancer cells with selective inhibitors of STAT3 and Akt protein." (PMID 34356634, 2021). "Moreover, IL-27 signaling in human ovarian cancer cells activated STAT1/STAT3 and induced the constitutive expression of IDO." (PMID 33418929, 2021). "The activation of the JAK/STAT3 pathway, reported to play an important role in multiple oncogenic processes, including tumour proliferation, differentiation, angiogenesis and survival, has a significant impact on the survival of ovarian cancer patients." (PMID 33809542, 2021). "A previous study demonstrated that dual inhibition of the EGFR and STAT3 pathways could lead to the simultaneous attenuation of multiple survival pathways in ovarian cancer." (PMID 34369236, 2021). "Recently, it has been demonstrated that both siRNA-mediated and pharmaceutical PARP inhibition leads to an increase in phosphorylation of STAT3 in ovarian cancer cell lines through dePARylation, a critical intrinsic property of PARP blockade, which is responsible for PD-L1 upregulation." (PMID 34956861, 2021). "Therefore, we compared p-STAT3 levels in six pairs of patient-matched ovarian carcinoma samples before and after PARPi treatment (three of them received Niraparib, two Rucaparib, and one Olaparib) from patients carrying germline BRCA mutations." (PMID 34956861, 2021). "The outcomes demonstrated that high STAT3/p-STAT3 expression in ovarian cancer tissue was correlated with a higher FIGO stage, a more advanced tumour grade, a higher risk of lymph node metastasis, non-mucinous ovarian cancer, shorter overall survival, and shorter progression-free survival." (PMID 34789292, 2021). "Macrophage secretory proteins induce ovarian cancer proliferation through the JAK2/STAT3 pathway." (PMID 34109184, 2021). "Likewise, parallel p-STAT3 and total STAT3 upregulation was observed in Paclitaxel and Cisplatin-resistant ovarian cancer cell lines, suggesting that elevated and prolonged STAT3 activation increases its own expression in drug-resistant cell lines." (PMID 34956861, 2021). "Blockade of the STAT3 pathway might be an effective strategy for increasing the therapeutic efficacy of targeting EGFR in ovarian cancer cells." (PMID 34369236, 2021). "In addition, IL-6 also enhanced the chemoresistance of ovarian cancer cells against cisplatin through the IL-6/STAT3/HIF-1α loop in vitro and in vivo." (PMID 33868231, 2021). "We provide evidence that post PARPi treatment phosphorylation of STAT3 in germline BRCA ovarian cancer patient biopsies is significantly increased not only in tumor cells but also in tumor-associated diverse immune cells, as well as cancer-associated fibroblasts (CAFs)." (PMID 34956861, 2021). "Reinartz derived a signal network model involving ovarian cancer cells and tumor associated macrophages (TAMs) linking IL-6, IL-10, and leukemia inhibitory factor (LIF) as cytokines that activate signal transducer and activator of transcription 3 (STAT3)." (PMID 34503128, 2021). "Four studies (5 trials) investigated the association between STAT3/p-STAT3 expression and ovarian carcinoma subtype (clear cell vs. non-clear cell) in 966 patients." (PMID 34789292, 2021). "Therefore, uniform criteria must be applied when determining STAT3/p-STAT3 expression to more reliably interpret its significance in ovarian cancer." (PMID 34789292, 2021). "Seven studies (8 trials) investigated the association between STAT3/p-STAT3 expression levels and ovarian carcinoma subtype (serous vs. nonserous) among a combined 1238 patients." (PMID 34789292, 2021).
ovarian carcinoma (continued). "The list of ovarian cancer-promoting agents upregulated in DIPS cells includes mediators of cancer cell proliferation (CCL11 – also via STAT3), migration (TGF-β1), invasion (PDGF-D, TGF-β1), epithelial-mesenchymal transition (TGF-β1, TSP-1), and angiogenesis (ANG-1)." (PMID 34674640, 2021). "Indeed, high expression of activated STAT3 has been shown to contribute to cisplatin resistance in ovarian cancer." (PMID 32252293, 2020). "In the chemotherapy treatment scenario, it is possible that the chemotherapy-induced acute secretory process, which causes the release of soluble factors (including TIMP-2), may control the activation of STAT3 in ovarian cancer cells." (PMID 33023532, 2020). "Also, EVs from epithelial ovarian cancer cells containing miRNA-141-3p promoted endothelial cell angiogenesis through activation of the JAK/STAT3 and NF-κB signaling pathways." (PMID 32384712, 2020). "Moreover, activated STAT3 is found located in focal adhesions known to be conducive to the motility of cell, and depletion of STAT3 decreased invasiveness of ovarian cancer cells." (PMID 31949487, 2020). "The activation of STAT3 signaling by HE4 reveals that HE4 may induce many of its oncogenic effects in ovarian cancer via this major pathway; however, a complete picture of STAT3-dependent, HE4-mediated gene expression remains to be determined." (PMID 32444701, 2020). "Moreover, STAT3 signaling promotes ovarian cancer resistance to cisplatin and paclitaxel, which can be reversed by either genetic or pharmacological STAT3 inhibition." (PMID 33335857, 2020). "We detected for the first time that BBI608 decreased the levels of Stat3 phosphorylation at tyrosine residue 705 in SKOV3 human epithelial ovarian cancer cells, and the phosphorylation Stat3 has exhibited close relation to tumour cells’ proliferation and transformation." (PMID 31778258, 2020). "Thus, it is crucial to have a full understanding of functions of STAT3 in ovarian cancer in order to develop effective therapeutic interventions for ovarian cancer." (PMID 31949487, 2020). "Therefore, here, we evaluate all existing evidence indicating functional CD44 and STAT3 cooperation in the context of tumor metastatic progression, therapy resistance and immunosuppression with the focus on ovarian cancer." (PMID 33335857, 2020). "We hypothesized At-EE inhibited the expression of IL-6 and VEGF from ovarian cancer cells through mediating NF-kB or STAT3." (PMID 32190078, 2020). "Moreover, it has been shown that knockdown of STAT3 in macrophages that were co-cultured with SKOV3 human ovarian cancer cells inhibited cell proliferation of SKOV3 through the downregulation of IL-6 and IL-10 of macrophages." (PMID 32283687, 2020). "Similarly, CAFs protect lung and ovarian cancer cells from cisplatin via increasing survivin by promoting STAT3 phosphorylation." (PMID 33080792, 2020). "In addition, resveratrol promoted the expression of the tumor suppressor gene, aplasia Ras homologue member I (ARHI), and inactivated the STAT-3 signal pathway in ovarian cancer cells." (PMID 32934709, 2020). "Interestingly, PDTC inhibited p-STAT3 activation, and stattic restrained NF-kB phosphorylation, which was an evidence for p-STAT3 and NF-kB mediating each other in ovarian cancer as a loop." (PMID 32190078, 2020). "Given that both CD44 and STAT3 are strongly implicated in the metastatic progression and chemoresistance of ovarian tumors, this review summarizes currently available evidence about functional crosstalk between CD44 and STAT3 in human malignancies with an emphasis on ovarian cancer." (PMID 33335857, 2020). "For instance, melittin induced apoptosis via death receptors and inhibited the JAK2/STAT3 pathway in ovarian cancer cells and also promoted apoptotic cell death via the mitochondrial signaling pathway, but not via the FAS/FASL pathway in human gastric (SCG-7901) cells." (PMID 32823904, 2020).
ovarian carcinoma (continued). "Stimulating ovarian cancer cells with IL-6 promotes STAT3 phosphorylation and cell migration." (PMID 31949487, 2020). "Moreover, IL-6 and IL-10 released by blood monocytes-derived TAMs activate the pro-survival STAT3 signaling in ovarian cancer cell lines and cancer cells isolated from patients’ ascites, keeping them alive." (PMID 32456078, 2020). "Moreover, targeting STAT3 phosphorylation by which curcumin inhibits invasion and metastasis of ovarian cancer cells." (PMID 31949487, 2020). "Similarly, an IL6R/STAT3/miR-204 feedback loop was correlated with the cisplatin resistance of epithelial ovarian cancer cells." (PMID 32872659, 2020). "They found that various ovarian cancer cell lines treated with cisplatin or carboplatin induced differentiation of macrophages into an M2-like phenotype characterized by elevated production of IL-10 and enhanced activation of STAT3 signaling factor." (PMID 32456078, 2020). "Interestingly, activation of STAT3 is involved in a CSC-like residual population of ovarian cancer cell after treatment with paclitaxel." (PMID 31949487, 2020). "Instead, the concurrent activation of multiple signaling pathways, including PI3K/AKT/mTOR, SRC, MEK/MAPK, and JAK/STAT3, appears to be more common in ovarian cancer and may play an important role in ovarian tumor growth." (PMID 32927828, 2020). "Moreover, abrogation of STAT3 activity has been shown to circumvent cisplatin resistance in ovarian cancer cells, making it a promising target to reverse cisplatin resistance in ovarian and other cancer types." (PMID 32252293, 2020). "This study primarily aimed to ascertain whether BBI608 exerts its anti‐cancer effects by modulating negative regulators of the Stat3 signalling pathway in epithelial ovarian cancer cells." (PMID 31778258, 2020). "Our results further show the mechanisms underlying the stimulation of proliferation and stemness of ovarian cancer cells by CD83, involving interaction with MAP3K7 and activation of MAPK signaling pathway, as well as downstream FOXO1/p21/CDK2/Cyclin B1 and STAT3/DKK1 cascades." (PMID 32823589, 2020). "In this review, we focus on the role of STAT3 in tumorigenesis of ovarian cancer and summarize the existing agents targeting STAT3 signaling that can be potentially developed as the strategies for ovarian cancer treatment." (PMID 31949487, 2020). "We observed that cells were enriched in G2/M phase after deletion of STAT3 in ovarian cancer." (PMID 31534498, 2019). "Herein, using CRISPR-Cas9 genome editing, we generated multiple STAT3 KO ovarian cancer cell lines." (PMID 31534498, 2019). "STAT3 in tumor cells may also enhance the expression of Rab family proteins to facilitate exosome release, which confers cisplatin resistance in ovarian cancer." (PMID 30927928, 2019). "In addition, when STAT3 was inhibited, the formation of VM structures was completely avoided, suggesting that p-STAT3 is an important regulator of VM in ovarian cancer cells." (PMID 31612116, 2019). "Inhibition of JAK2/STAT3 signaling pathway induces apoptosis in ovarian cancer cells." (PMID 31540495, 2019). "In conclusion, our findings reported that knockdown of HE4 suppresses aggressive cell growth and malignant progression of ovarian cancer by inhibiting the JAK/STAT3 pathway, which provides valuable insights to contribute to develop novel HE4-targeted therapies." (PMID 31477564, 2019). "Based on these results, we could conclude that Jagged1/STAT3 crosstalk is a critical mechanism for EMT in cisplatin‐resistant ovarian cancer." (PMID 30993885, 2019). "Therefore, the combination of cisplatin with HO-3867 is effective in selective targeting of the platinum-resistant ovarian cancer cells by inhibiting STAT3 activity." (PMID 31766284, 2019).